PPARG (peroxisome proliferator activated receptor gamma)
Diseases named in the same sentence as PPARG in open-access papers (continued):
Sharing a sentence is not in itself a finding about the gene and the disease.
cancer (continued). "Several potential downstream targets of PPARγ for mediating antitumor effects of PPARγ have been identified in various cancer cell types." (PMID 18551185, 2008). "The results suggest that increased PPARγ signaling can act as a pro-survival factor by enhancing cancer cell proliferation and blocking the ability of the cell to undergo apoptosis." (PMID 19061500, 2008). "Existingdata suggest that peroxisome proliferator-activated receptor-gamma (PPARγ) is apotential target ally to cancer chemopreventive agents." (PMID 18779870, 2008). "Recent reports from both in vitro and in vivo studies are inconsistent and suggest that endogenous activation of PPARγ plays a much more complex role in initiation and progression of cancer than previously thought." (PMID 19061500, 2008). "PPARγ status is only now beginning to be examined inthe in vivo cancer setting,however the TZDs have been used in a variety of clinical trials, although notdirectly related to PPARγ activation." (PMID 19096712, 2008). "As indicatedabove, the PPARγ agonist rosiglitazone also decreased CXCR4 expression on humancolorectal cancer cells, congruent with an effect of 15dPGJ2 throughPPARγ." (PMID 18779872, 2008). "Accumulating evidence suggests that PPARγ activatorsmight have clinical therapeutic benefit in the treatment of cancers." (PMID 18725985, 2008). "PPARγ has pleiotropic effects on survival and proliferation of multiple cell types, including cancer cells, and is now subject of intensive preclinical cancer research." (PMID 19043603, 2008). "This PPARγ agonist induced apoptosis in both PTEN intactand PTEN null cancer cell lines and decreased proliferation of the endometrialhyperplastic lesions in a PTEN(+/−)murine model." (PMID 18779870, 2008). "Recently, PPARγ has emerged as a promising target for cancer therapy based on the fact that its activation by synthetic ligands such as TZDs have been shown to induce cell cycle arrest, apoptosis and differentiation in many human malignancies." (PMID 19061500, 2008). "In this article,we reviewed literature on the roles of PPARγ in cancer with an emphasis on those thatsuggest a proneoplastic function for the receptor." (PMID 18784849, 2008). "Activation of PPARγ by agonists such asthiazolidinediones (TZDs) has been shown to have anticancer effect in vitro and in vivo in many cancer types." (PMID 18509497, 2008). "Many studies have revealed that TZDsexert PPARγ-independent effects on induction ofapoptosis in various cancer cells." (PMID 18615184, 2008). "We herein review the synergistic antitumor effects produced by the combination of the PPAR, especially PPARγ, ligands plus other agents, especially retinoids, in a variety of human cancers." (PMID 18528526, 2008). "Induction of differentiation and apoptosis in cancer cells by ligands of PPARγ is a novel therapeutic approach to malignant tumors." (PMID 18725985, 2008). "PPARγ agonists induce apoptosis using fatty acid derivatives, TZDs and tyrosine-based agonists in several cancer cell types." (PMID 18261208, 2008). "Theresults obtained from these studies would concretely determine if Rositreatment is advantageous for cancer patients by upregulating PTEN expressionthrough PPARγ." (PMID 19096712, 2008). "Numerous other examples of differentialeffects among PPARγ agonists exist, but it is worth stressingthat n-3 PUFAs inhibit the metabolism of n-6 PUFAs to products that promote thegrowth of cancer cells such as PGE2, 5-HETE, and leukotriene B4." (PMID 18769551, 2008). "This review summarizes what is known about PPARγ inhibitors and cancer cell death, with emphasis on the tubulin phenotype and PPAR-dependence, and identifies potential mechanisms of action." (PMID 18509498, 2008). "The prominent role of PPARγ in regulating cellular differentiationprompted a great effort to investigate the function of PPARγ in cancer field." (PMID 18551185, 2008).
cancer (continued). "While PPARγ activation in NHU cell cultures inducesdifferentiation, someselective PPARγ and most dual-acting PPARα+γ agonists causebladder cancer in rats." (PMID 19197366, 2008). "Accordingly, the involvement of PPARγ and its ligands in regulation of apoptosis of cancer cells have been extensively studied." (PMID 18615184, 2008). "Of the known PPARγ inhibitors, only T0070907, GW9662, and BADGE have been tested for their effects on cancer cell death; all three can cause cell death in multiple cancercell types at high-micromolar concentrations." (PMID 18509498, 2008). "While PPARα was the first PPAR to be associated with tumorigenesis, the emerging awareness of the PPARγ-cancer connection is evidenced by the fact that 4 out of 7 reviews in this issue focus on PPARγ." (PMID 19590598, 2008). "This synergy is associated with the reductionof multiple members of the metallothionein gene family expression, whichplay a role in the resistance of certain cancers to platinum-based drugs by PPARγ." (PMID 18528526, 2008). "An in-depth analysis of the role of TZDs againstcolon cancer can be facilitated through development of tissue-specific PPARγ knockout mice." (PMID 18779870, 2008). "Genetic mouse models using targeted knockouts of PPARγ in either cancer cells or stromal compartments will also beinformative." (PMID 18509496, 2008). "Among natural products, triterpenoids,flavononoids, carotenoids, and linoleic acid are the most extensively studiedas cancer chemopreventives and have invariably been found to operate as PPARγ activators." (PMID 18779870, 2008). "Overall, PPARγ appears to be a prevalent target ally to cancer chemopreventive agents and therefore pursuing research in this area is of great relevance." (PMID 18779870, 2008). "Depending on cell types or ligands, induction of apoptosis in cancer cells by PPARγ ligands can be either PPARγ-dependent or -independent." (PMID 18615184, 2008). "Activation of peroxisome proliferator-activated receptors γ (PPARγ) induces diverse effects on cancer cells." (PMID 18261208, 2008). "Similar results were obtained in studies in which PC3, CaCO-2, and T47D cancer cells were inhibited by both PPARγ agonists and antagonists separately and in co-treatments." (PMID 18947424, 2008). "Especially PPARγ and its agonists have been demonstrated toinduce antineoplastic effects in several types of cancer." (PMID 18725982, 2008). "Increasing evidence implicates PPARγ in the divergent effects of n-3 and n-6PUFAs in cancer cells and point to a growth inhibitory role for PPARγ." (PMID 18769551, 2008). "Thediscovery that PPARγ has a marked inhibitory effect oncultured cancer cells stimulated a large number of studies using a variety ofcancer cells." (PMID 18670615, 2008). "Compounding thesedifficulties is the issue of studying PPARγ signaling in cancer biology, which isintrinsically an unstable and evolving disease environment." (PMID 18528521, 2008). "A strategy to address this issue is the useof molecular approaches, either overexpressing or silencing PPARγ in cancer cells to complement studies with pharmacologicalagents." (PMID 18509496, 2008). "In contrast, PPARγ staining was seen in the islets surrounding cancers, butnot in islet cells from normal pancreatic tissues obtained from multiorgandonors." (PMID 19190780, 2008). "In contrast to our study, activated ERαby E2 lowers both basal and ligand-stimulated PPARγ-mediated gene reporter activity in MCF-7 cancer cell culture." (PMID 18769493, 2008). "The ability of PPARγ to induce cellular differentiation and the existence of FDA-approved PPARγ agonists encourage the exploration of possibilities to activate or inactivate PPRE containing modules to arrest cancer progression." (PMID 18551184, 2008). "In efforts to explore the role of PPARγ activation in cancer, most of the recent studies employed pharmacological approaches." (PMID 19061500, 2008).
cancer (continued). "In vitro studies have shown that omega-3 PUFAs inhibit cell proliferation and induce apoptosis in cancer cells through various pathways but one of which involves PPARγ activation." (PMID 18769551, 2008). "Recent studies haveidentified the heparan sulfate proteoglycan, syndecan 1, as a target for PPARγ in human breast and prostate cancer cells." (PMID 18769551, 2008). "Interpreting the effects of the cancer-targeting PPARγ inhibitors is difficult, since they can act as activators or inhibitors, depending on the concentration used." (PMID 18509498, 2008). "Another question thatwas addressed was the impact of IL-6 on the responses of the MM lines to PPARγ antagonists, since this is a cytokine thatplays a central role in the pathogenesis and progression of MM, as well asother cancer types." (PMID 18779871, 2008). "The outcome of the crosstalk between TGFβ and PPARγ inbreast carcinoma patients should be dependent on stage of the particular breastlesion." (PMID 18645617, 2008). "Activated PPARγ has been shown able to stimulate differentiation and apoptosis in cancer cells from various origins." (PMID 17767717, 2007). "PPARγ plays certain role in anti-inflammation, colon carcinogenesis, and cancer development in the inflamed colon." (PMID 17506908, 2007). "Nevertheless, in contrast with results generated in vitro, data concerning PPARγ expression in human cancer specimens raised questions about the anti-neoplastic activity of the receptor in vivo." (PMID 17767717, 2007). "PPARγ is expressed in many cancers, including colon, breast, andprostate, and specific PPARγ agonists, such as thiazolidinediones,are generally considered antiproliferative in these settings." (PMID 17389773, 2007). "Activation of PPARγ has been showed to inhibit proliferation and induce apoptosis in a variety of malignant tumours." (PMID 16495926, 2006). "Whilst these findings are consistent with PPARγ-independent growth inhibition observed in some cancer types, it has been clearly demonstrated in other cases that thiazolidinedione agonists and 15dPGJ2-induced growth inhibition is PPARγ-dependent." (PMID 16519808, 2006). "PPARγ is overexpressed in multiple cancer types and the role of this receptor in carcinoma progression has been widely studied using the family of high affinity thiazolidinedione PPARγ agonists." (PMID 16519808, 2006). "In other cancer types, it is becoming evident that growth inhibition can be ligand dependent, and cannot always be attributed to PPARγ activation." (PMID 16519808, 2006). "Clearly the response to PPARγ ligands and the involvement of PPARγ in these effects differs widely amongst carcinoma types and thus each carcinoma type must be specifically examined." (PMID 16519808, 2006). "PPARγ is also expressed in a number of epithelial neoplasms, such as cancers in colon, breast, and prostate." (PMID 15892897, 2005). "In certain cancer cells, ligand activation of PPARγ results in the inhibition of the release of inflammatory cytokines by cancer cells." (PMID 15583697, 2005). "In contrast, 26 out of 28 carcinomas studied were positive for PPARγ expression with staining confined to cytoplasmic and nuclear regions." (PMID 15583697, 2005). "Clinical trials exploring the feasibility of using PPARγ agonists in the treatment of human cancers are underway." (PMID 15467764, 2004). "COX-2 protein was detected in eight of the 12 carcinomas, whereas PPARγ protein was detected in only two cases." (PMID 15266333, 2004). "The frequency of COX-2 and PPARγ detection was significantly increased and decreased as lesions progressed to carcinoma, respectively." (PMID 15266333, 2004). "The strategy of activation of PPARγ to induce differentiation or maturation in cells is increasingly receiving attention in cancer treatment during the last few years." (PMID 14562008, 2003). "An association has been suggested between PPARγ and COX-2, which has also been implicated in various human cancers, including head and neck SCCa." (PMID 12454768, 2002).
cancer (continued). "Induction of differentiation and apoptosis in cancer cells by ligands of PPARγ is a novel therapeutic approach against malignant tumours." (PMID 11953889, 2002). "Other mediators that have been implicated in PPARγ-independent properties of 15-PGJ2 and can potentially have a similar function in cancer cells include AP-1, MAP kinase, and reactive oxygen species." (PMID 12454768, 2002). "Notably, favorable interactions were identified with PPARG and CARM1, supporting therapeutic relevance in inflammation and cancer, alongside additional targets associated with neurodegeneration and bone metabolism." (PMID 42075901, 2026). "Accumulating evidence has shown that PPARγ exerts pro-cancer effects in immune cells." (PMID 41304753, 2025). "A more nuanced understanding of the context-dependent functions of PPARγ may reveal novel avenues for selectively harnessing its benefits while minimizing its oncogenic potential in the management of cancer cachexia." (PMID 41476922, 2025). "One possible explanation for the different responsivenessof cancer cell lines to PFOS-induced cell proliferation may be dueto the expression of PPARγ which also binds PFOS." (PMID 40066943, 2025). "These compounds are used to target different nuclear receptors of cancer which includes peroxisome proliferator-activated receptor gamma (PPARγ), toll-like receptor 4 (TLR4), brain-derived neurotrophic factor (BDNF), and peroxisome proliferator-activated receptor alpha (PPARα)." (PMID 41459064, 2025). "Its pleiotropic actions are underpinned by the regulation of key signaling pathways (e.g., NF-κB, MAPK, STAT, and PPARγ), modulation of cell polarization and activation, and restoration of immune homeostasis in preclinical models of inflammation, infection, and cancer." (PMID 41164200, 2025). "Most believe PPARγ activation can inhibit cancer development through various mechanisms." (PMID 39875357, 2025). "By disentangling the tissue- and context-specific actions of PPARγ, it may be possible to transform this controversial receptor from a double-edged sword into a clinically actionable target for the management of cancer cachexia." (PMID 41476922, 2025). "Given its diverse functions, PPARγ serves as a critical regulator of metabolic homeostasis and may influence both the development and potential therapeutic modulation of cancer cachexia." (PMID 41476922, 2025). "Emerging evidence highlights the paradoxical role of PPARγ in cancer cachexia." (PMID 41476922, 2025). "However, increasing evidence suggests that they exert significant anti‐cancer effects through both PPARγ‐dependent and PPARγ‐independent mechanisms." (PMID 40387523, 2025). "For example, PPARγ in myeloid cells has been shown to promote cancer progression and metastasis." (PMID 41304753, 2025). "Crosstalk of PPARγ with metabolic regulators and nuclear receptors in cancer cachexia." (PMID 41476922, 2025). "In our prior research, we targeted PPARγ in two human cancer cell lines (MCF-7 and HepG2)." (PMID 41403929, 2025). "Currently, diverse PPARγ-activating derivatives have been synthesized for human cancer treatment." (PMID 41403929, 2025). "Although clinical data remain limited, emerging studies suggest that PPARγ-targeted therapies may ameliorate metabolic dysfunction and maintain adipose tissue integrity in patients with cancer cachexia." (PMID 41476922, 2025). "In cancer cachexia, PPARγ may mediate a dynamic interplay with AMPK, mTOR, and PGC-1α, orchestrating the balance between anabolic and catabolic processes." (PMID 41476922, 2025). "Therapeutic opportunities of PPARγ Agonists in cancer cachexia." (PMID 41476922, 2025). "In addition, PPARγ agonists have been proven to have the ability to prevent and treat certain types of cancer." (PMID 38542198, 2024). "Furthermore, a growing body of evidence indicates that PPARγ activation prevents cancer in tissues such as the colon, breasts, and lungs." (PMID 38397426, 2024).
cancer (continued). "Additionally, there was a notable downregulation of PPARγ, which plays a crucial role in insulin sensitization, glucose uptake, and enhancement of energy metabolism in HT-29 cancer cells." (PMID 38674023, 2024). "Nevertheless, the precise involvement of PPARγ in cancer biology is not well understood." (PMID 39148124, 2024). "It was recently reported that lncRNA small nucleolar RNA host gene 1 (SNHG1) is expressed in several cancer types such as breast, colorectal, pancreatic and neuroblastoma as a competitive endogenous RNA and can inhibit PPARγ expression to promote bladder cancer pathogenesis." (PMID 39199690, 2024). "Loss-of-function somatic missense mutations of PPARG have also been described in cancer but are not particularly common." (PMID 39195246, 2024). "The conflicting roles of PPARγ agonists in regulating cancer cell proliferation may result from the off-target effects of thiazolidinediones." (PMID 39695138, 2024). "Finally, there was a strong downregulation of PPARγ gene, essential for insulin sensitization and glucose uptake, potentially impairing multiple metabolic pathways utilized by cancer cells for growth and proliferation." (PMID 38674023, 2024). "Consequently, PPARγ agonists are currently being considered as a potential target for cancer therapy." (PMID 38254789, 2024). "Notably, the role of PPARγ in tumors is complex, and its outcome appears to be influenced by factors such as cancer type, the stage of development, and specific genetic and molecular background." (PMID 38786003, 2024). "The expression of PPARA, PPARD and PPARG in a total of 32 types of cancers was determined." (PMID 38529307, 2024). "Given this association, there is growing interest in strategies to raise adiponectin levels through interventions such as peroxisome proliferator-activated receptor gamma (PPARγ) agonists or vigorous aerobic exercise as potential therapeutic approaches in obesity-related diseases and cancers." (PMID 38339282, 2024). "Notably, these genes, such as PPARG, HK2, and PDK1, play critical roles in the regulation of aerobic glycolysis in cancer cells, which is associated with the IDH phenotype in GBM cells." (PMID 39530009, 2024). "Interestingly, PPARγ seems to have opposing effects on cancer progression among different cells, with anti-oncogenic effects on cancer cells but pro-oncogenic effects on cancer-associated immune cells." (PMID 38397426, 2024). "Binding to the alternate site of PPARγ by fatty acids, produced by de novo biosynthesis or massively derived from diet, may support anti-cancer effects." (PMID 39199386, 2024). "PPARγ is a well-recognized key regulator of adipocyte and macrophage differentiation processes; however, it also plays a central role in lipid and glucose metabolism in cancer cells." (PMID 38137407, 2023). "We observed significant heterogeneity in PPARG expression across different types of cancer." (PMID 38044948, 2023). "In particular, about 30% of pediatric cancers harbor BRAF/RAS mutations, while gene fusions are present in up to 60% of cases, mainly in younger patients with PTC, usually involving RET or NTRK1/3, as also ALK, BRAF and PPARG." (PMID 37046700, 2023). "Second, although co-localisation analyses of PPARG and cancer endpoints provided low posterior probabilities for shared causal variants, it should be noted that this may also reflect limited power." (PMID 37171501, 2023). "Secondly, the precise significance of PPARG expression in various types of cancer and its precise role in immune regulation within these tumors remain unclear." (PMID 38044948, 2023). "In this regard, cancer-derived miRNA-27 may suppress PPARγ and C/EBPα expression and may induce their change of phenotype into CAAs, in CRC cases, while a miRNA-27b-3p overexpression has been accompanied by an inhibition of browning in WAT." (PMID 37760840, 2023). "Receptor PPARG inhibits the growth of cancer cells, including NSCLC." (PMID 38001428, 2023).